LEP (leptin)
Diseases named in the same sentence as LEP in open-access papers (continued):
Sharing a sentence is not in itself a finding about the gene and the disease.
Obesity (continued). "A role of leptin and its receptors in the control of food intake and energy expenditure was suggested several years ago by findings of severe obesity in leptin-deficient ob/ob mice or in db/db mice expressing mutated, non-functional LepRs on all cells throughout the body." (PMID 37217565, 2023). "Besides, we have also discussed the protein hormones adiponectin and leptin, which are the major associated factors between obesity and cognitive dysfunction." (PMID 37363537, 2023). "However, in our study, the highest area under the curve in identifying obesity risk was found for leptin concentration." (PMID 37373485, 2023). "Among genetic models of obesity, mice deficient in leptin signaling are the most used." (PMID 37007087, 2023). "Thus, obesity, characterized by hyperleptinemia and central leptin resistance, directly increases the risk of HCC." (PMID 37266440, 2023). "Insufficient energy intake (for instance, during fasting) leads to a decrease in leptin levels: this in turn stimulates intense hunger, causing an increase in food intake, which may subsequently lead to obesity." (PMID 37452264, 2023). "Obesity in middle-aged individuals may precede dementia as a vascular risk factor and decreased neuroprotective effects of leptin due to obesity contribute to Alzheimer’s disease." (PMID 36835164, 2023). "Leptin (LEP) is an obesity-associated adipokine associated with tumor cell growth." (PMID 37282602, 2023). "Furthermore, we found a number of studies describing the association of leptin with obesity, but a small number of studies investigating the role of leptin in normal healthy, and moderate- and high-overweight people." (PMID 37240998, 2023). "Intentional weight loss (including diet/exercise/surgery), especially if greater than 10%, is able to reverse the proinflammatory state linked to obesity, e.g., reducing the levels of C-reactive protein, tumor necrosis factor-α, interleukin-6 and the leptin-to-adiponectin ratio." (PMID 37686769, 2023). "Moreover, if we consider that all the monogenic obesities identified so far concern exclusively genes encoding hypothalamic proteins (except for leptin) mainly involved in the regulation of appetite, we can conclude that obesity is a neurobehavioral disease." (PMID 37375686, 2023). "In OA patients, obesity was significantly associated with an increase in LEP promoter methylation." (PMID 36835984, 2023). "Thus, leptin and LR seem to be emerging novel players that are playing a central role in the MetS, in that LR is not only associated with obesity but also contributes to obesity and independently affects IR." (PMID 36984562, 2023). "In relation to our findings, three possible mechanisms linking PA and AT could be speculated: i) obesity ii) insulin resistance iii) increased leptin levels and associated immune dysregulation." (PMID 37009276, 2023). "Complete leptin deficiency causes early-onset severe obesity." (PMID 36674935, 2023). "The bias towards obesity via the melanocortin pathway may also underlie the observed drastic differences in the impact on physiology between low and high leptin levels." (PMID 37069175, 2023). "Leptin resistance is considered a major risk factor for obesity." (PMID 37798684, 2023). "The dysregulation in the secretion of adipokines, such as leptin, which occurs in obesity states, could be associated with an increase in inflammatory factors already at an early age." (PMID 37242271, 2023). "In animal models, altered leptin signalling during gestation may predispose the fetus to leptin resistance and obesity development in later life." (PMID 36678336, 2023). "In addition, a cross-sectional study revealed that obesity raises the risk of AITD by affecting a loop involving leptin." (PMID 37197658, 2023). "In other words, excessive leptin concentration causes obesity." (PMID 37691744, 2023). "Increased leptin levels are linked to obesity and metabolic syndrome." (PMID 36902307, 2023).
Obesity (continued). "Leptin resistance is linked to obesity and its associated metabolic imbalances." (PMID 37373992, 2023). "While the animal study did not have a weight loss intervention, the observed positive association between obesity, leptin levels, and breast cancer recurrence provided a biological rationale for conducting weight loss interventions on breast cancer survivors with overweight or obesity." (PMID 37571390, 2023). "Major adipokines involved in the pathogenesis of obesity-related knee osteoarthritis include adiponectin, which appears to have a protective effect, as well as leptin, resistin and visfatin, which are associated with higher pain scores and more severe structural damage." (PMID 38275369, 2023). "However, leptin resistance can occur to increase the predisposition of individuals to diet-induced obesity, which in turn contributes to a further increase in leptin levels and aggravation of existing leptin resistance in a vicious cycle." (PMID 37894869, 2023). "Likewise, it has been shown that one of the main causes of hyperleptinemia is obesity, which in turn causes leptin resistance due to lipotoxicity." (PMID 37299591, 2023). "Obesity is associated with changes in glucose metabolism, leptin resistance, and hepatic steatosis." (PMID 37168577, 2023). "However, leptin replacement has only been shown to reverse obesity in leptin-deficient conditions and its use in obese individuals with elevated leptin levels shows null or limited efficacy." (PMID 36674935, 2023). "However, little is understood about how leptin acts on the leptin receptor (obR) in neutrophilic airway inflammation in obesity-associated asthma." (PMID 37488474, 2023). "However, HFD-induce obesity is associated with leptin resistance, which is characterized by high circulating leptin levels." (PMID 36819708, 2023). "A limiting number of studies have investigated the effect of HFD only during lactation, but animal studies have shown that HFD feeding to lactating dams predisposes the offspring for obesity and related metabolic abnormalities by impairing neurodevelopment, leptin sensitivity, or inflammation." (PMID 37485363, 2023). "We hypothesize that identification of the critical transmitter signaling components underlying the leptin-responsive neural circuit is crucial for the development of more efficient therapeutics for obesity." (PMID 37043384, 2023). "Genetic models have primarily centered on perturbation of the leptin signaling pathway, in which either the appetite-suppression hormone leptin (Lepob/ob) or its receptor (Leprdb/db) is deficient, leading to rapid onset obesity from overfeeding." (PMID 37648285, 2023). "Restoring leptin sensitivity through such interventions could play a significant role in addressing various reproductive dysfunctions linked to obesity." (PMID 38264286, 2023). "Leptin has been implicated in the pathogenesis of obesity, MetS, OA, and inflammation." (PMID 37703108, 2023). "Secreted by adipose tissues, leptin and adiponectin are known to be associated with obesity." (PMID 37960308, 2023). "Nevertheless, weight‐pairing in mice has demonstrated that obesity may attenuate the morphological changes in femur and lumbar vertebral bone associated with leptin deficiency." (PMID 37786973, 2023). "Likewise, dysfunction of the primary cilia in the CNS has been associated with hyperphagia, hypothermia, leptin resistance and obesity." (PMID 38027481, 2023). "It has been suggested that adipose tissue could oversecrete irisin to tackle obesity-induced metabolic dysregulation, thereby explaining the observed positive association between irisin and leptin in SO." (PMID 37175880, 2023). "Another plausible mechanism is involved in obesity-linked leptin resistance." (PMID 37468882, 2023). "In addition, LCN2 acts as a key mediator of HSC activation in leptin-deficient obesity via α-SMA/MMP9/STAT3 signaling, further exacerbating NASH." (PMID 37784089, 2023).
Obesity (continued). "We speculated that it may be due to the facts that Caucasians were more prone to be obese than other populations, and obesity may be associated with high level of leptin." (PMID 36914629, 2023). "However, this same system has been demonstrated to break down in obesity, where LEP deficiency and/or LEP resistance hinder the ability of the body to balance energy intake and expenditure." (PMID 37224770, 2023). "Therefore, obesity and diabetes-associated leptin resistance should be conditions with ACTH and cortisol excess." (PMID 38260129, 2023). "Nevertheless, given the contribution of hyperleptinemia to the low-grade systemic inflammation during obesity, it is suggested that high leptin levels may predispose obese patients to a cardiovascular disease risk." (PMID 38136564, 2023). "Decreased leptin levels were associated with BC risk in women with obesity." (PMID 37512149, 2023). "Moreover, in patients with overweight and obesity, weight loss is associated with a significant elevation of that index due to a progressive elevation of adiponectin and reduced leptin levels." (PMID 37391843, 2023). "Moreover, obesity was associated with an increase in the production of leptin as a proinflammatory and a reduction in adiponectin as an anti-inflammatory mediator." (PMID 36865485, 2023). "Existing studies have also documented that adipocyte hormone such as leptin may be an underline modulator on the HPT axis under obesity status.Therefore, further studies are warranted to take into account iodine status and hormones." (PMID 37875982, 2023). "One explanation could be that leptin resistance is a consequence of deficiency of some other adipokine that is deficient in obesity and rises after SSFR." (PMID 37021835, 2023). "However, prolonged exposure of human chondrocytes to leptin, as typically seen in obesity, has been associated with diminished cell viability." (PMID 38001998, 2023). "Therefore, it is possible that the impact of this genetic variant on leptin and obesity varies in these populations, so it is important to consider the ancestry of the cohort studied in future studies." (PMID 36833305, 2023). "Moreover, the hyperleptinemia appears causative considering that leptin levels were increased both before the onset of obesity and after weight normalization by calorie restriction." (PMID 37064917, 2023). "Studies have shown that obesity is caused by the host’s resistance to leptin." (PMID 37992054, 2023). "LEP, which acts as a growth factor in colonic epithelial cells, might underlie the observed associations among obesity, physical activity, and colon cancer." (PMID 37282602, 2023). "In addition, human adipose-derived MSC-based therapy alleviated serum leptin levels and/or the leptin-adiponectin ratio, which is an important index for predicting the risk of obesity-related disorders." (PMID 36750692, 2023). "Interestingly, obesity is associated with selective leptin resistance, which can lead to increased hyperphagia and rapid weight gain." (PMID 36837766, 2023). "Obesity can also promote LC along with hepatitis virus infection, leptin, and other risk factors." (PMID 38012596, 2023). "Leptin is associated with both obesity and breast cancer risk." (PMID 37160903, 2023). "Leptin, which is synthesized in adipose tissue and influences body weight, may be linked to this bidirectional relationship between obesity and depression, due to higher levels of adipose in depressed individuals." (PMID 37443383, 2023). "Thus, similarly to other adipokines like leptin, resistin and IL-6 overproduced by the adipose tissue during obesity, MCP-1 plays a causal role in inflammation, insulin resistance and atherosclerosis during obesity." (PMID 38136564, 2023). "In addition, leptin-induced mTORC1 activation was significantly suppressed under Slc7a5 deficiency prior to the onset of obesity." (PMID 36862514, 2023).
Obesity (continued). "However, in obesity and aging, leptin malfunction is associated with decreased sensitivity of tissues to leptin." (PMID 38068822, 2023). "Recent work has investigated whether changes in the function of ArcN NPY or POMC neurons in males with obesity underlie sensitization to the sympathoexcitatory effects of leptin and/or its metabolic partner, insulin." (PMID 36769012, 2023). "Several single-nucleotide polymorphisms (SNPs) found in the LEP (Leptin) gene may be associated with serum leptin concentration related to the pathophysiology of obesity and its complications among specific ethnic groups." (PMID 37978555, 2023). "However, in obesity, blood leptin levels are permanently elevated, which is associated with leptin resistance." (PMID 38203600, 2023). "Leptin resistance increases food intake owing to loss of leptin function, which promotes obesity." (PMID 36835164, 2023). "Obesity and elevated leptin levels are associated with insulin resistance and type 2 diabetes." (PMID 37484968, 2023). "Furthermore, obesity in DM is linked to higher leptin levels which influences endothelial dysfunction and the development of ASCDs." (PMID 37946116, 2023). "In terms of the close relationship between leptin and obesity, it was reasonable to predict that high level of leptin may increase the risk and severity of asthma through its interaction with obesity." (PMID 36914629, 2023). "Whether cognitive impairment (and possibly Alzheimer’s disease) associated with obesity is due to leptin resistance (similar to cognitive deficits in leptin-deficient models) is still an uncertainty." (PMID 38137454, 2023). "Finally, IN leptin proved to be useful in relieving the sleep-disordered breathing associated with obesity." (PMID 37371113, 2023). "Poor zinc status in obesity is associated with inflammation, oxidative stress and both lipid and glucose metabolism, with zinc supplementation shown to improve body weight management, potentially through regulation of leptin levels." (PMID 35138503, 2023). "Leptin-deficient OB/OB mice and leptin receptor-deficient db/db mice are two monogenic rodent models that have been widely studied and used as preclinical models that mimic the conditions of obesity and T2D development." (PMID 37650104, 2023). "Obesity is also associated with elevated leptin levels, contributing to renal damage." (PMID 37371050, 2023). "Considering this information, the higher systemic levels of adiponectin and lower leptin observed in this study may have been associated with a decrease in subclinical inflammation in participants with severe obesity and MetS." (PMID 37571250, 2023). "Leptin, which is overrepresented in populations with obesity, could also be responsible for this association." (PMID 37189944, 2023). "While many studies avoid linking the methylation status of the leptin gene to obesity in a cause-and-effect context, it is worth noting that a correlation has been made between the observation of hypomethylation of the leptin gene and the obesity phenotype." (PMID 37899888, 2023). "Indeed, investigation and understanding of the phenotypic differences associated with leptin signaling would give us new insight into and knowledge of new therapeutics to treat obesity and diabetes or their related diseases." (PMID 35563777, 2022). "For example, pleiotropy may occur when shared genetic variants influence obesity-related traits and ↑WS depression through common pathways such as inflammation and/or leptin system dysregulation." (PMID 32624019, 2022). "Since the concentration of leptin is directly proportional to the body fat volume, therefore, generally low leptin concentration is unable to fully activate neurocircuits involved in feedback inhibition of the feeding process and causes obesity." (PMID 35388304, 2022).
Obesity (continued). "In obesity studies, genetically modified models (such as Lepob/ob leptin-deficient mice) and germ-free mouse models are indispensable because they allow interventions that cannot be performed in humans to provide evidence of how gut bacteria influences host metabolism." (PMID 35782067, 2022). "Moreover, several studies reported inverse associations between breast milk leptin level and infant weight gain suggesting a role of milk-borne leptin in the early regulation of body weight and the prevention of adult obesity." (PMID 36558383, 2022). "It is considered that sequence variants in the LEP gene may be involved in the pathomechanism of obesity development." (PMID 35684517, 2022). "Leptin, as well as other pro-inflammatory cytokines, such as interlukin-6 and tumor necrosis factor, are increased in obesity and may be linked to cholangiocarcinogenesis because cholangiocytes express their receptors." (PMID 35884542, 2022). "Furthermore, adipose tissue is the main source of leptin and other adipokines causing inflammatory states mainly in obese people, thus, reducing fat mass and increasing physical exercises would improve obesity-related OA." (PMID 35270000, 2022). "In addition to the lack of control of the mechanisms of the hypothalamic–pituitary axis of hunger and satiety, triggered by increased resistance to leptin and insulin, predisposing to obesity." (PMID 36361448, 2022). "Obesity and diabetes are both associated with metabolic changes such as increasing circulating levels of leptin and insulin, which may adversely impact development." (PMID 36337853, 2022). "Leptin genetics based on molecular background could be of interest in determining genetic susceptibility profiles related to obesity and CRC in terms of prevention, prognostic treatment, or management strategies." (PMID 35563103, 2022). "Leptin has multiple beneficial effects at physiological concentrations, and one of the major risk factors for obesity is leptin resistance, which occurs as a result of impaired leptin transport, leptin signaling, or the hypothalamic neural circuit that regulates energy homeostasis." (PMID 36499312, 2022). "Further, humans with loss-of-function mutations in leptin showed low BP despite severe obesity." (PMID 35056647, 2022). "This review summarizes the current knowledge on leptin genetics and its potential relationship with the main pathogenic pathways of obesity and CRC, in an attempt to understand the molecular mechanisms of these associations, in the context of inconsistent and contradictory data." (PMID 35563103, 2022). "The ob/ob mice are genetically deficient in the Ob gene, and leptin (expressed protein of the Ob gene) deficiency results in extreme obesity, hyperphagia, insulin resistance, and dyslipidemia with reduced energy expenditure, and these mice are easily prone to MetS." (PMID 35742829, 2022). "In conclusion, homocysteine could cause neuronal leptin resistance by triggering endoplasmic reticulum stress, which would be one of the mechanisms of obesity." (PMID 36512575, 2022). "However, studies demonstrated that severe obesity develops from rare genetic mutations that affect genes of both leptin and its receptor, and lead to congenital leptin deficiency or leptin resistance." (PMID 36452324, 2022). "Many mechanisms have been proposed for the development of obesity in DS including increased serum leptin levels associated with increased appetite as the leptin hormone affects the hunger and satiety centers in the brain, decreases energy expenditure, and decreases physical activity." (PMID 36232301, 2022). "In addition, recent studies showed that mice deficient in this enzyme were resistant to diet-induced obesity, increased insulin and leptin sensitivity." (PMID 35637957, 2022). "Whilst this may suggest that leptin is a driving factor that promotes MM in obesity, it may also reflect an underlying importance of dietary composition in promoting MM progression." (PMID 35908046, 2022).